ENSG00000283515 (novel protein)
Gene: Protein-coding gene on chromosome 19 (58,228,914 to 58,315,183, forward strand). Ensembl gene ENSG00000283515.
Genetic constraint (gnomAD): Missense variants: 77 observed, 92.56 expected, observed/expected ratio (o/e) 0.83, 90% interval 0.69 to 1.01. Synonymous variants: 34 observed, 32.3 expected, observed/expected ratio (o/e) 1.05, 90% interval 0.8 to 1.4.